PIEZO2 (piezo type mechanosensitive ion channel component 2)
Diseases named in the same sentence as PIEZO2 in open-access papers (continued):
Sharing a sentence is not in itself a finding about the gene and the disease.
dysautonomia (1 paper, 2023). An acute or chronic disorder, affecting the sympathetic or parasympathetic nervous system. "Dysautonomia is suggested to be the direct result of the proprioceptive Piezo2 irreversible microinjury in ALS, not to mention the finding that in fact the loss of Piezo2 vagal neurons put an end to baroreceptor sensing and reflex." (PMID 36979911, 2023).
Dystonia (1 paper, 2023). An abnormally increased muscular tone that causes fixed abnormal postures. "A similar mechanism could play a central role in peripherally-induced dystonia, and future studies should investigate the role of PIEZO2 overexpression in patients with peripherally-induced dystonia and the putative role of early botulinum toxin injection." (PMID 37008994, 2023).
endometriosis (1 paper, 2026). The growth of functional endometrial tissue in anatomic sites outside the uterine body. "The ion channels Piezo1 and Piezo2 primarily work as mechanosensors and mechanotransducers but also have functions that could participate in the clinical hallmarks of endometriosis." (PMID 41594706, 2026). "Thus, we investigated the occurrence and localization of Piezo1 and Piezo2 in healthy human endometrium and in endometriosis using immunohistochemistry." (PMID 41594706, 2026).
epilepsy (1 paper, 2025). A brain disorder characterized by episodes of abnormally increased neuronal discharge resulting in transient episodes of sensory or motor neurological dysfunction, or psychic dysfunction. "Notably, epilepsy is not a common feature of Marden–Walker syndrome, but the presence of abnormal EEG findings in this case suggests a possible extension of the neurological phenotype associated with PIEZO2 variants." (PMID 41153369, 2025).
Gait ataxia (1 paper, 2023). A type of ataxia characterized by the impairment of the ability to coordinate the movements required for normal walking. "Our results demonstrate that PIEZO2 is a therapeutic target for AS and provide proof of concept that increasing LA in the diet enhances channel activity and ameliorates gait ataxia in a mouse model of AS." (PMID 36859399, 2023). "Here, we show that PIEZO2 function is reduced in AS and that a safflower oil diet, enriched in linoleic acid (LA), increases PIEZO2 activity, mechano-excitability, and ameliorates gait ataxia in a mouse model of AS." (PMID 36859399, 2023).
incontinence (1 paper, 2021). "Piezo2 expression was limited to a small subset of superficial umbrella cells, yet male Piezo2-KO mice exhibited incontinence (i.e., leakage) when their voiding behavior was monitored during their active dark phase." (PMID 34464353, 2021).
Insulin resistance (1 paper, 2025). Increased resistance towards insulin, that is, diminished effectiveness of insulin in reducing blood glucose levels. "As a result, impaired Piezo2–Piezo2 crosstalk-induced autonomic dysregulation and impaired Piezo2–Piezo1 crosstalk could prevail, resulting in insulin resistance, because Piezo1 has a role in glucose-induced insulin secretion." (PMID 40076941, 2025).
irritable bowel syndrome (1 paper, 2021). Irritable bowel syndrome (IBS) is a chronic functional condition of the lower gastrointestinal (GI) tract characterized by abdominal pain or discomfort and disordered bowel habit (diarrhea, constipation, or fluctuation between the two). "Piezo2 in the colon is significantly negatively correlated with the visceral sensitivity of irritable bowel syndrome (IBS)." (PMID 34722345, 2021).
keloid (1 paper, 2025). An irregularly shaped, elevated mark on the skin caused by deposits of excessive amounts of collagen during wound healing. "To investigate the role of PIEZO2‐expressing fibroblasts in keloid tissue, we analyzed the global gene expression on fibroblasts isolated from keloid tissue (case 14) from PIEZO2 high‐expression (PIEZO2hi) and PIEZO2 low‐expression (PIEZO2lo) groups." (PMID 40742741, 2025). "In this study, we report increased expression of PIEZO2 in fibroproliferative keloid tissue and elucidate that PIEZO2‐positive cells are involved in the formation of keloid vessel structures and fibrous stroma as a pathological scar." (PMID 40742741, 2025). "Concerning this finding, VECs, LECs, and fibroblasts spreading around the vascular structures in keloid tissue expressed PIEZO2, contributing to increased PIEZO2 expression in the fibroproliferative tissue of keloids." (PMID 40742741, 2025). "For the following reasons, we also consider that PIEZO2‐positive cells in the fibroproliferative tissue of keloids should be distinct from Merkel cells in the epidermis." (PMID 40742741, 2025). "Another hallmark of PIEZO2‐positive cells was the presence of both POSTN and PIEZO2‐positive cells, spreading from the lymphatic vessels into the dermal interstitium of keloid tissue." (PMID 40742741, 2025). "Given the increased PIEZO2 expression associated with recurrence of keloids in the short term, and the possible role of PIEZO2‐positive cells in the histopathological architecture of keloids, we performed scRNA‐seq analysis to characterize PIEZO2‐positive cells in keloid tissue." (PMID 40742741, 2025). "Additionally, PIEZO2 expression levels were significantly higher in recurrent keloids than in non‐recurrent keloids (3,032.5 ± 1,090.2 versus 1,241.9 ± 860.7, p = 0.032)." (PMID 40742741, 2025). "Targeting PIEZO2 may be effective in the treatment of keloids, as earlier studies pointed out that proliferation of fibroblasts and myofibroblasts in response to mechanical stimulation through PIEZO1 could serve as a therapeutic target." (PMID 40742741, 2025). "Therefore, since PIEZO2‐positive cells are highly expressed specifically in keloids and are deeply involved in their recurrence and activity, we propose that the pathogenesis of keloids is constructed by PIEZO2‐positive cells." (PMID 40742741, 2025). "However, PIEZO2‐positive cells in the fibroproliferative tissue of keloids should be distinguished from the ‘dermal Merkel cell’ used in earlier studies." (PMID 40742741, 2025). "In this context, our findings on PIEZO2 expression in keloid tissue open new avenues for research aimed at elucidating the functional activation of the PIEZO2 receptor and evaluating the effects of its inhibition or remission of keloid tissue using molecular and cellular biology techniques." (PMID 40742741, 2025). "We observed that higher expression levels of PIEZO2 were correlated with keloid recurrence." (PMID 40742741, 2025). "Therefore, further studies are needed to investigate the influence of keloid‐related PIEZO2‐positive cells on morphological diversity in keloid tissue during the differentiation and maturation process." (PMID 40742741, 2025). "Notably, the clustering of PIEZO2‐positive cells with small immune cells was more pronounced in proliferative (active) areas of the keloid than in the central, more mature area (inactive) of the keloid." (PMID 40742741, 2025). "In line with developing novel keloid treatments, we have initiated a clinical study focusing on PIEZO2 expression to establish unique molecular signatures (biomarkers) for monitoring the therapeutic efficacy of PIEZO2‐targeted interventions." (PMID 40742741, 2025). "Indeed, the upregulated PIEZO2 gene expression in keloids aligns with earlier studies demonstrating higher expression of COL1A2 and POSTN in keloids than in normal skin tissue." (PMID 40742741, 2025).
keloid (continued). "Additionally, our results show that intercellular communication between PIEZO2‐positive cells and immune cells may contribute to the pathology of keloids." (PMID 40742741, 2025). "Additionally, the upregulation of collagen gene expression in Fibroblast2 and the activation of signaling pathways for ECM production may support the idea that PIEZO2 expression contributes to the characteristic histological features in abnormally proliferating scar tissue in keloids." (PMID 40742741, 2025). "Moreover, to investigate changes in the expression of the two mechanosensitive channels, we compared the POSTN expression previously reported to increase keloids with PIEZO1 and PIEZO2 expression in the same 30‐case dataset." (PMID 40742741, 2025).
kidney cancer (1 paper, 2022). Primary or metastatic malignant neoplasm involving the kidney. "Our results revealed that kidney cancer with high expression of Piezo2 exhibited better clinical benefits of therapy against the PD-1 and PD-L1 axis." (PMID 35991548, 2022).
liver fibrosis (1 paper, 2025). "MF2 cells specifically expressed liver fibrosis-related genes AGTR1, CYGB, PIEZO2, and LPL, and MF5 cells specifically highly expressed immune-related genes TRAC, CD3D, GZMB, and FCGR3A." (PMID 40949143, 2025).
lymph node metastases (1 paper, 2022). "For patients suffering from KIRP, PAAD, and CRC, the Piezo2 expression levels were lower in patients without lymph node metastases than those with lymph node metastases." (PMID 35991548, 2022).
melanoma (1 paper, 2022). A malignant, usually aggressive tumor composed of atypical, neoplastic melanocytes. "At the same time, we found that Piezo2-knockout was an important factor of tumor-killing mediated by NK cells in melanoma (Freeman 2019 NK) and (Kearney 2018 NK_20)." (PMID 35991548, 2022).
microphthalmos (1 paper, 2021). "Three of the candidate genes discovered in our GWAS for eye size – PRSS56, ADAMTS19, and PIEZO2 – are of particular interest by virtue of their known or suggested role in causing nanophthalmos or microphthalmos." (PMID 34698770, 2021).
multiple sclerosis (1 paper, 2023). A progressive autoimmune disorder affecting the central nervous system resulting in demyelination. "This theory could be analogous to impaired crosstalk between axonal Piezo2 and Piezo1 of oligodendrocytes in the central nervous system in multiple sclerosis (MS)." (PMID 37108693, 2023).
neuralgia (1 paper, 2021). "Our study demonstrated that the up-regulation of Piezo2 in the pain afferent neurons following trigeminal nerve injury may play a role in the development of the neuralgia." (PMID 33893246, 2021).
Obesity (1 paper, 2019). Accumulation of substantial excess body fat. "Interestingly, adipose Piezo2 was also upregulated in obesity." (PMID 31263454, 2019).
orthostatic hypotension (1 paper, 2026). Sudden fall of the blood pressure of at least 20/10 mm Hg when a person stands up. "Knockout of Piezo2 and/or ablation of PIEZO2 neurons in vagal ganglia eliminates this heartbeat-coupled nerve activity, causes orthostatic hypotension and compromises cardiovascular stability during trauma-induced blood loss." (PMID 41606321, 2026).
overactive bladder (1 paper, 2023). Symptom of overactive detrusor muscle of the urinary bladder that contracts with abnormally high frequency and urgency. "Our finding may also indicate that manipulations targeting Piezo2 may be potential therapeutic approaches for overactive bladder patients." (PMID 37227654, 2023).
Pain (1 paper, 2023). An unpleasant sensory and emotional experience associated with actual or potential tissue damage, or described in terms of such damage. "In light of these results, the Piezo2 antagonist could be effective in the treatment of endothelial cell-dependent vascular neuropathic pain." (PMID 38054043, 2023).
prediabetes (1 paper, 2025). "Moreover, this exercise regimen appears to facilitate the unidentified novel Piezo2-mediated ultrafast proton-based synchronization pathways, thereby promoting more optimal insulin regulation in response to mechanotransduction, even in individuals with prediabetes." (PMID 40137805, 2025).
Pulmonary hypoplasia (1 paper, 2023). "In contrast, tracheal occlusion in in vivo mouse model was an inductor of α-SMA and MLC2 expression at the later canalicular stage, suggesting that the PIEZO1/PIEZO2 pathway may be a potential target for the treatment of fetal pulmonary hypoplasia." (PMID 36740669, 2023).
pulpitis (1 paper, 2024). Inflammation of the dental pulp. "Collectively, these results suggested the potential roles of PIEZO1 and PIEZO2 in inflammation and pain in irreversible pulpitis, which pave the way for further investigations aimed at clarifying the underlying mechanisms and achieving corresponding clinical outcomes for irreversible pulpitis." (PMID 38627713, 2024). "Overall, these data revealed that PIEZO1 expression increased while PIEZO2 expression decreased in irreversible pulpitis." (PMID 38627713, 2024). "This study demonstrated the upregulation of PIEZO1 and the downregulation of PIEZO2 in irreversible pulpitis and revealed the potential relation of PIEZO1 and PIEZO2 to inflammation and pain." (PMID 38627713, 2024). "Given that PIEZOs play a vital role in inflammation and pain, the current study assumed that PIEZO expressions were altered in irreversible pulpitis, and primarily compared expression patterns of PIEZO1 and PIEZO2 between irreversible pulpitis and normal pulp." (PMID 38627713, 2024).
rectal cancer (1 paper, 2019). A primary or metastatic malignant neoplasm that affects the rectum. "The other risk haplotype on chromosome 18 overlapped with part of the gene PIEZO2, and at least one rectal cancer family (family 1425) is likely to have this 220-kb haplotype based on genotyping of the parent–child pair." (PMID 30952955, 2019).
respiratory failure (1 paper, 2024). The significant impairment of gas exchange within the lungs resulting in hypoxia, hypercarbia, or both, to the extent that organ tissue perfusion is severely compromised. "Mutations in the PIEZO2 gene have been associated with proprioception defects, respiratory failure, and muscle weakness." (PMID 38339995, 2024).
sensory impairments (1 paper, 2023). "The sex-differential role of Piezo2 in human sensory impairments has also been suggested in case studies." (PMID 37061508, 2023).
Stroke (1 paper, 2023). Sudden impairment of blood flow to a part of the brain due to occlusion or rupture of an artery to the brain. "Consistent with previous findings 71, responses to gentle stimuli (air puff and brush stroke) were markedly attenuated in somatosensory neurons from Piezo2cKO mice, corroborating the role of Piezo2 in the sense of touch." (PMID 37541196, 2023).
trigeminal neuralgia (1 paper, 2021). Trigeminal neuralgia is a nerve disorder that causes a stabbing or electric-shock-like pain in parts of the face. "Our findings implicated a possibility to cure the trigeminal neuralgia with a noninvasive targeting therapy instead of open-brain surgery in the future as long as we could block the IL-6/Piezo2 pathway." (PMID 33893246, 2021).
type 2 diabetes (1 paper, 2015). "Our study found that SNPs located in PIEZO2 on chromosome 18p were also associated with high YZ scores among patients with type 2 diabetes." (PMID 26169365, 2015).
uveitis (1 paper, 2023). An inflammatory process affecting a part of or the entire uvea. "Current authors suggest that the impaired Piezo2-Piezo1 crosstalk also has a role in the light gateway reflex activation in AS, leading to uveitis; however, this mechanism is not the subject of this manuscript." (PMID 37895134, 2023).
vaginal endometriosis (1 paper, 2026). "In ectopic endometriosis, there was an increase in the intensity of Piezo1 regardless of location; Piezo2 only showed a net increase in the ovarian and vaginal endometriosis foci." (PMID 41594706, 2026).
tumor (32 papers, 2013 to 2026). "One possible explanation is that PIEZO2 expression is inversely associated with tumor cell stemness and mutational burden in these subgroups." (PMID 41327436, 2025). "Aberrant expressions of both Piezo1 and Piezo2 genes are in many ways linked to tumor development and metastases." (PMID 36837670, 2023). "To identify the associations between Piezo2 and cancers, we explored the expression differences of Piezo2 in tumor tissues." (PMID 35991548, 2022). "Second, external validation studies were warranted to confirm the associations between Piezo2 expression and tumor prognosis." (PMID 35991548, 2022). "In this study, we interrogated that the expression levels and epigenetic alterations of Piezo2 were associated with tumor staging, the prognosis of patients, and immunotherapy for various cancers." (PMID 35991548, 2022). "From a mechanistic perspective, direct functional evidence remains limited, but clinical correlations suggest that PIEZO2 may modulate mechanotransductive signaling linked to tumor differentiation and microenvironmental stiffness." (PMID 41327436, 2025). "The poor prognosis of the PIEZO2 overexpression group might be attributed to an imbalance in immune function and internal environment, resulting in a loss in anti-tumor potential." (PMID 38216574, 2024). "Finally, the differential PIEZO2 genes in GC were mostly implicated in the processes of inflammation, immunological response, and tumor metastasis, according to functional analysis." (PMID 38216574, 2024). "This might be because of the reduced tumor stemness and gene mutation degree in individuals with GC who express high levels of PIEZO2." (PMID 38216574, 2024). "The findings imply that PIEZO2 may be adversely linked with tumor cell stemness and mutation in GC patients, resulting in a better prognosis in poorly differentiated tumors in GC patients with high PIEZO2 expression." (PMID 38216574, 2024). "Consequently, Piezo2 promoter hypermethylation is not only an LSCC risk factor but also a marker for tumor progression and the presence of metastases, a prediction marker of a patient’s poorer survival, and a possible therapeutic target." (PMID 36837670, 2023). "In GC, the expression profile and prognostic value of PIEZO2 remain heterogeneous and context dependent, reflecting complex interactions between tumor differentiation, stemness, and the immune microenvironment." (PMID 41327436, 2025). "Beyond its role in metastasis, emerging evidence implicates PIEZO2 in the modulation of radioresistance and tumor immunity." (PMID 41327436, 2025). "These mechanistic disparities underscore the importance of tumor context in determining the biological and clinical impact of PIEZO2 and suggest that therapeutic strategies should be tailored to its expression and epigenetic status in each malignancy." (PMID 41327436, 2025). "Meanwhile, paclitaxel—a microtubule-targeting agent commonly used in cancer chemotherapy—has recently been found to enhance Piezo2 signaling responses, thereby participating in the regulation of the tumor microenvironment." (PMID 41282026, 2025). "Emerging evidence highlights the tumor-suppressive potential of PIEZO2 inhibition across diverse malignancies." (PMID 41327436, 2025). "This downregulation correlates with key clinicopathologic markers, including estrogen receptor (ER), progesterone receptor (PR), and HER2 status, suggesting that PIEZO2 expression is closely aligned with tumor hormonal signaling profiles." (PMID 41327436, 2025). "While Piezo1 promotes processes such as epithelial remodeling and tumor invasion via pathways like RhoA/ROCK and YAP/TAZ, Piezo2 is more associated with sensory neuron activity, immune modulation, and tumor aggressiveness." (PMID 42211053, 2025). "The dualistic nature of PIEZO2, which functions as both an oncogenic accelerator and a tumor suppressor, complicates its categorization as a universal biomarker or therapeutic target." (PMID 41327436, 2025).